IPAN (inhibitor of RIG-I/TRIM25 mediated viral protein degradation ncRNA)
Gene: Long non-coding RNA gene on chromosome 1 (88,462,792 to 88,478,313, forward strand). Ensembl gene ENSG00000286758.
Gene Ontology:
Biological process: SRP-dependent cotranslational protein targeting to membrane, signal sequence recognition
Cellular component: signal recognition particle, endoplasmic reticulum targeting